TLR4 (toll like receptor 4)
Diseases named in the same sentence as TLR4 in open-access papers (continued):
Sharing a sentence is not in itself a finding about the gene and the disease.
Sepsis (continued). "However, Cobalt alloy particle induced inflammatory responses as determined by IL-1β and TNF-α secretion in vitro were not as pro-inflammatory relative to TLR4 PAMP agonist despite high levels of PAMP agonist (LPS) used at levels corresponding to sepsis (>500pg/mL)." (PMID 27467577, 2016). "Our results demonstrate that blockade of either TLR2 or TLR4 significantly decrease systemic inflammatory responses and lethality especially when used in combination with antibiotics, representing a specific preclinical setting at which blockers of TLR may be useful in patients with sepsis." (PMID 26147469, 2015). "Meanwhile, dexmedetomidine also inhibited the expression of TLR4 and MyD88 and the activation of ERK1/2 and NF-κB in the lung tissues of CLP-induced septic rats, indicating that the anti-inflammation effect of dexmedetomidine in sepsis maybe base on TLR4/MyD88/ERK1/2/NF-κB signal pathway." (PMID 25929655, 2015). "Another possibility could be that plasma from patients with severe sepsis induces platelet-neutrophil interactions in a TLR4-dependent fashion leading to the production of NETs, whereas TLR4 does not seem to play an important role in the clearance of B. pseudomallei." (PMID 26215706, 2014). "Among the ten identified human Toll-like receptors (TLRs), TLR4 and TLR2 are the two major contributors to the pathogenesis of sepsis 9, 10, as they sense Gram-negative and Gram-positive bacteria, respectively, to launch inflammatory reactions." (PMID 40963927, 2025). "Cilastatin was originally developed to inhibit the renal metabolism of imipenem by DHP-I, and it is not a known anti-inflammatory agent or direct ligand of TLR4 or NLRP3, although it protects against sepsis-induced AKI by decreasing inflammation." (PMID 40869248, 2025). "However, TLR4 inhibitors have not been as effective as expected in treating sepsis, and the clinical effect of endotoxin adsorption remains to be determined, suggesting that another TLR4-independent pathway may be more critical for LPS-induced endotoxemia and endotoxic shock." (PMID 37700349, 2023). "Firstly, we found that CD14+ monocytes from pneumonia-induced sepsis patients had considerably greater levels of the proteins TLR4, NLRP3, ASC1, cleaved caspase-1, IL-1, and GSDMD in contrast to pneumonia patients without sepsis and healthy people." (PMID 36923408, 2023). "MAPK14 concentrations were significantly higher in children with sepsis than in controls (median 96.418 vs. 20.177 ng/ml, P < 0.001), whereas HMOX1 (P = 0.367) and TLR4 (P = 0.506) were not significantly different." (PMID 35844488, 2022). "Hence, we hypothesized that sepsis molecules (LPS, cytokines, and some viable bacteria) pass through the damaged BBB and upregulate miR370-3p in brain cells, partly through the activation of TNF-α receptor (TNFR) and TLR-4 by TNF-α and LPS, respectively, that enhance mitochondrial injury." (PMID 35628259, 2022). "Murine models of sepsis-induced ALI mimic TLR3, TLR4, TLR7 and NLRP3 activation but, unlike the human disease, also activate TLR2 and TLR9." (PMID 33672738, 2021). "Therefore, the effect of CaD to decrease CD14 and TLR4 expression could offer one mechanism to explain why CaD inhibits NF-κB and suppresses the release of downstream NF-κB activation products—TNFα, IL-1β, IL-6, and MCP-1 in animal models of sepsis and diabetic nephropathy and retinopathy." (PMID 34829669, 2021). "In sepsis induced by Gram-negative bacteria, LPS from Gram-negative bacteria, CD14, and TLR4 form a complex to activate several intracellular signaling pathways including NF-κB, MAPKs (such as p38), JNK, and Erk." (PMID 32889432, 2020). "Clinical trials with a TLR4 antagonist and TNF-α inhibitor have shown no improvement of the mortality rate of severe sepsis patients; however, those trials did not examine long-term muscle function." (PMID 28742154, 2017).
Sepsis (continued). "As assessed by scoring the sepsis type (sepsis and severe sepsis vs. septic shock) and SOFA and APACHE II scores, we found that the TLR4 rs11536889 genotypes were also not related to the septic disease severity at sepsis onset." (PMID 24950711, 2014). "Both allele and genotype distributions of the other 14 SNPs in TLR2, TLR4, TLR9, MyD88, and TOLLIP did not vary significantly between sepsis patients and healthy controls." (PMID 21219635, 2011). "As these receptors are responsible for recognizing components of gram-negative (TLR4) and gram-positive (TLR2) bacteria, they have become a major target to blunt the pro-inflammatory response in sepsis." (PMID 20707930, 2010). "Moreover, it is not known if TLR4 inhibition would reduce cardiac inflammation when the heart is exposed to a complex mixture of PAMP, mimicking sepsis." (PMID 39853914, 2025). "Moreover, during sepsis, gram-positive bacterial molecules acting through TLR2 and gram-negative LPS acting through TLR4, can function through parallel signaling pathways to impair MTAL transport." (PMID 36674930, 2023). "Thus, two TLR4 antagonists TAK-242 and Eritoran reached clinical trials as anti-sepsis agents, unfortunately both failed to suppress cytokine levels or improve the survival of septic patients." (PMID 35370674, 2022). "Moreover, feces EVs containing both Gram-positive and Gram-negative bacterial EVs are capable of inducing sepsis-like systemic inflammation and this effect is mediated through both TLR2 and TLR4, respectively." (PMID 34281154, 2021). "In sum, all that can be said in general about innate activation in sepsis is that TLR2, TLR4, TLR5, TLR7 and NLRP3 can be, but are not necessarily, activated, while TLR9 may or may not be downregulated." (PMID 33672738, 2021). "Although LPS stimulation could activate both NK and NKT cells to secrete cytokine IFNγ through the TLR4 signaling pathway, SRG3 overexpression appeared to diminish the activation of NK cells but not NKT cells in LPS-induced sepsis." (PMID 33809795, 2021). "Three genes were differentially expressed in uncomplicated sepsis patients but not in severe sepsis; IL-8 expression was lower than healthy controls (p = 5.0×10−4, Mann Whitney), whereas TLR2 and TLR4 expression was higher (p = 0.013 and p = 0004, respectively, Mann Whitney)." (PMID 25343379, 2014). "As we used a model of polymicrobial (gram-positive and-negative) sepsis, changes in CD14 expression, increased by TLR4- and/or TLR2-mediated signaling, may reflect infection with both gram stain groups." (PMID 23302299, 2013). "To determine whether the absence of TLR2, TLR4 and MyD88 affects the mortality in AKI induced by CLP, we evaluated the survival of all mice for 192 hours after the induction of sepsis." (PMID 22655058, 2012). "Although direct blockade of TLR4 may potentially serve as an effective therapeutic strategy for acute pulmonary inflammation and ALI, blockade of TLR4 must be applied with caution, because TLR4 blockade is not beneficial for patients with sepsis." (PMID 26070954, 2015). "Lipopolysaccharide (LPS), the Gram-negative bacterial outer membrane glycolipid, induces sepsis through its interaction with LPS-binding protein (LBP) or CD14 prior to subsequent formation of a complex with myeloid differentiation protein-2 (MD-2) and Toll-like receptor 4 (TLR4)." (PMID 19816595, 2009).
Obesity (606 papers, 2008 to 2026). Accumulation of substantial excess body fat. "Overall, current evidence supports a central role for TLR4 as a mediator of obesity-associated metabolic inflammation, highlighting TLR4 and its downstream pathways as promising targets for preventing or treating obesity related metabolic diseases." (PMID 41698753, 2026). "Research has found that, in diabetic models, EGCG indirectly inhibits the stability of TLR4 mRNA by promoting Fat Mass and Obesity-Associated Protein degradation, thereby reducing TLR4 protein expression." (PMID 40266904, 2025). "SFA-mediated islet inflammation impairs beta cell function via TLR4 signalling and, consistently, TLR4 deficiency protects pancreatic islets against the deleterious effects of obesity." (PMID 40387904, 2025). "In obesity, specific GM3 species are up-regulated and enhance TLR4 signaling, thus impacting chronic inflammation associated with obesity and metabolic syndrome." (PMID 41301440, 2025). "Female mice that lack TLR4 are protected against insulin resistance associated with high-fat-induced obesity." (PMID 40985048, 2025). "Beyond its classical activation by LPS, TLR4 can also be stimulated by saturated free fatty acids during the hyperlipidemic state associated with obesity and chronic HFD intake." (PMID 41226745, 2025). "Mutations or deficiency of TLR4 have been shown to confer partial protection against the metabolic consequences of obesity, mitigating insulin resistance and systemic inflammation." (PMID 41226745, 2025). "We found a significant association between TLR4 and obesity in IBC subjects as well as a positive correlation with Ki-67 expression when comparing IBC versus non-IBC cases." (PMID 40647480, 2025). "To investigate this relationship, we examined the impact of TLR4 deficiency on the enteric nervous system (ENS) of the small intestine in a mouse model of high-fat diet (HFD)-induced obesity." (PMID 41226745, 2025). "Recognition of saturated fatty acids by TLR4 triggers the activation of the innate immune signaling pathway, which is associated with increased inflammation in obesity and necessary for lipid-induced insulin resistance." (PMID 38999906, 2024). "TP lower systemic LPS levels and curb the LPS-activated TLR4/NF-kappa B pathway, reducing inflammation linked to obesity." (PMID 39606571, 2024). "Obesity causes changes in the microbiota, resulting in an increase in LPS, which in turn activates macrophages and microglia by TLR4, worsening inflammation." (PMID 39064298, 2024). "After LPS binds to TOLL-like receptor 4 (TLR4), it activates the early pro-inflammatory responses associated with obesity." (PMID 39200098, 2024). "Based on previous studies, the interaction of TLR4-NF-κB with components in the STING-IRF3 pathway results in different outcomes in obesity-related metabolic disorders, and the mechanisms underlying these outcomes have not been fully elucidated." (PMID 38164186, 2024). "In high-fat diet conditions, only obesity-resistant mice display elevated Tlr4 expression linked to ileal inflammation." (PMID 38474087, 2024). "On the other hand, the increase in FFAs in obesity is linked with the activation of Toll-like receptor 4 (TLR4) signaling in adipocytes, which induces the inflammatory process." (PMID 39339765, 2024). "This study firstly demonstrates the association between a novel SNP, TLR4 rs1928295, and overweight/obesity in Han Chinese children aged 7–12 years." (PMID 37571378, 2023). "Thrombospondin-1 (TSP1) contributes to obesity-associated inflammation via activating Toll-like receptor 4 (TLR4)." (PMID 37964189, 2023). "Inflammation and insulin resistance, caused by obesity, is reduced in TLR4-/- mice by preventing insulin signal transduction and nitric oxide generation." (PMID 36674680, 2023). "TLR4 deficiency prevents diet-induced obesity, which has been found to be related to the reduced ability of fatty acids to induce inflammatory signaling in fat cells or tissues and macrophages." (PMID 37571378, 2023).
Obesity (continued). "So, we chose to explore the novel locus TLR4 rs1928295, which would be an important supplement to the research on TLR4 gene polymorphism of overweight/obesity occurrence in China." (PMID 37571378, 2023). "In conclusion, the TT genotype of TLR4 rs1928295 is a potential risk factor for overweight/obesity and lipids profile in Chinese children." (PMID 37571378, 2023). "Obesity is associated with low-grade systemic inflammation and increased levels of inflammatory markers such as the toll-like receptor 4 (TLR4), tumor necrosis factor-alpha (TNF-α), and IL-6." (PMID 37056543, 2023). "Recently we showed that short-term exposure (five days) to PM2.5 was sufficient to increase the expression of inflammatory markers such as Tlr4, Ikbke, and Tnf alpha in the hypothalamus causing leptin resistance and obesity at long-term of PM2.5-exposure." (PMID 37082122, 2023). "The study on the association between TLR4 gene polymorphism and obesity is very rare at present, and this paper opens up a new territory for it." (PMID 37571378, 2023). "As for obesity, several TLR4 polymorphisms are linked to a higher probability of developing glaucoma, and this is proof that supports the key role of TLR4 in the pathogenesis of this disease." (PMID 36674680, 2023). "No study has been conducted on the connection between overweight/obesity and TLR4 rs1928295 polymorphisms." (PMID 37571378, 2023). "Our results indicated that the TT genotype of TLR4 rs1928295 is a potential risk factor for obesity in Chinese Han children and is associated with dietary patterns." (PMID 37571378, 2023). "We chose C3H/HeJ mice as they are known to have a perturbed inflammatory response due to a functional mutation in the TLR4 gene and are resistant to diet-induced obesity." (PMID 35410390, 2022). "TLR4 deficiency mitigates obesity-induced adipose tissue inflammation and systemic insulin resistance in mice." (PMID 35490239, 2022). "Aberrant activation of TLR4 plays an essential role in inflammation caused by obesity, which is involved in several disorders (e.g., hypertriglyceridemia, hyperinsulinemia, and cardiovascular disease)." (PMID 36014370, 2022). "SFA, which is known to cause hypothalamic inflammation and obesity, activates TLR4 to induce an inflammatory response." (PMID 36188456, 2022). "The activation of Toll-like receptor 4 (TLR4) by saturated fatty acids is the cause of obesity-induced inflammation, but this is suppressed by epigallocatechin-3-gallate in green tea." (PMID 35276992, 2022). "TLR4 signaling initiates a cascade of events that cause NF-κB activation, and it has been identified as a trigger of obesity-associated chronic inflammation." (PMID 35967316, 2022). "Several studies originally showed that TLR4 deficiency prevented diet-induced obesity (DIO) and insulin resistance in mice." (PMID 36555322, 2022). "Individuals with obesity have higher levels of TLR2 and TLR4 expression in their adipose tissue, indicating that these receptors are implicated in the inflammation-related signaling associated with obesity." (PMID 36421371, 2022). "TLR4 represents the link between fatty acids, immunity, and inflammation and has been linked to the pathogenesis of obesity, insulin resistance, and NAFLD." (PMID 36360622, 2022). "Transplantation assays of adipose tissue revealed that obesity due to ob mutation or HFD promoted NLRP3 inflammasome-dependent IL-1β production by adipose tissue macrophages via the TLR4-MyD88 signaling pathway (top)." (PMID 35163498, 2022). "Tlr4 is a member of the Toll-like receptor family, and has been linked with obesity, inflammation, and changes in the gut microbiota." (PMID 35866635, 2022). "Certain S100 proteins, namely S100A4, S100A8/S100A9 heterodimer, and S100B, have been implicated in the pathophysiology of obesity-promoting macrophage-based inflammation via toll-like receptor 4 and/or receptor for advanced glycation end-products ligation." (PMID 35328627, 2022).
Obesity (continued). "By activating ER stress, antipsychotics such as olanzapine activate hypothalamic astrocytes and Toll-like receptor 4 signaling, thereby causing inflammation and weight gain/obesity." (PMID 36188456, 2022). "Recently, it was reported that the pathogenesis of OLZ-induced obesity is associated with hypothalamic inflammation induced by toll-like receptor-4 signaling in astrocytes (another type of glial cell in the central nervous system)." (PMID 36313357, 2022). "67LR is also essential in manifesting the anti-inflammatory effect of EGCG through attenuating Toll-like receptor 4 (TLR4) signaling, and a potent target for relieving inflammation caused by obesity." (PMID 36014370, 2022). "An attenuation of obesity-induced adipose tissue inflammation has already been demonstrated in C3H/HeJ mice (which have a mutation in TLR4) when compared to their controls after ingestion of a HFD." (PMID 35488354, 2022). "Further, TLR4 signaling is presumed to be associated with COVID-19-related severities in patients with pre-existing comorbidities such as diabetes, obesity, atherosclerosis, hypertension, and aging." (PMID 34067609, 2021). "The recognition of saturated fatty acids by the Toll-Like Receptor (TLR) family of pattern recognition receptors, specifically TLR4, is another mechanism associated with obesity induced metainflammation." (PMID 34445300, 2021). "Additional studies proposed that HFDs are sufficient to cause obesity-related inflammation by altering gut microbiota composition, increasing intestinal permeability, and inducing TLR4 signaling." (PMID 33498671, 2021). "The role of TLR4 in liver disease is well established as an activator of obesity-associated inflammation and insulin resistance, thus serving as a therapeutic target for the treatment of type 2 diabetes." (PMID 33777102, 2021). "In accordance, TLR4 loss-of-function mutation or intracerebroventricular injection of a TLR4 neutralizing antibody reduces obesity and leptin resistance." (PMID 34201844, 2021). "In this regard, a recent study found that lipid-induced LPS-mediated inflammation through TLR4 is associated with obesity and worsened by PCOS." (PMID 33714202, 2021). "Inhibiting TLR4 signaling seems to be a pragmatic therapeutic approach for CRC or obesity-associated CRC treatment." (PMID 34385421, 2021). "TLR4 is one of the toll-like receptors, a family of proteins playing a role in the innate immune system, and is believed to be an important trigger of obesity-associated inflammatory response." (PMID 34975827, 2021). "Animal models showed that obesity-associated metabolic endotoxemia induced AT inflammation through an LPS/toll-like receptor 4 (TLR4)-mediated mechanism." (PMID 34680216, 2021). "Although the mechanisms underlying obesity-associated cardiac dysfunction are not fully understood, several factors, including toll-like-receptor 4 (TLR4) have been implicated." (PMID 33762947, 2021). "One interesting target for probiotic modulation is TLR4 signaling, which is central in metabolic endotoxemia and linked to obesity, as TLR4-deficient mice are resistant to HFD-triggered obesity." (PMID 32218248, 2020). "TLR4 and MyD88 both play prominent roles in supporting low-grade inflammation in obesity, and deficiency in either protein attenuates obesity and metabolic alterations caused by a HFD." (PMID 33603741, 2020). "The TLR4-mediated signal transduction pathway plays an essential role in cardiac structural and electrical remodeling caused by obesity." (PMID 32491968, 2020). "Increased plasma LPS and LBP levels in subjects with obesity and T2D negatively correlated with muscle insulin sensitivity as well as reduced incidence of heart disease and T2D in subjects with TLR4 gene polymorphisms." (PMID 32295104, 2020). "It was demonstrated that in PCOS, lipid-induced LPS-mediated inflammation through TLR-4 was associated with obesity and worsened by PCOS." (PMID 31906930, 2020).